FAM224A (family with sequence similarity 224 member A)
Synonyms: formerly NCRNA00230A; LINC00230A
Gene: Long non-coding RNA gene on chromosome Y (18,326,047 to 18,353,210, forward strand). Ensembl gene ENSG00000233522.
Diseases named in the same sentence as FAM224A in open-access papers:
FAM224A is named in the same sentence as 2 diseases in open-access papers, as found by Europe PMC text mining. Sharing a sentence is not in itself a finding about the gene and the disease. The quoted sentences say what the papers report.
glioma (1 paper, 2019). A benign or malignant brain and spinal cord tumor that arises from glial cells (astrocytes, oligodendrocytes, ependymal cells). "Our present data revealed that A1CF and FAM224A were obviously upregulated in glioma tissues and cells." (PMID 31186064, 2019). "In our study, we discovered that overexpression of A1CF remarkably upregulated FAM224A expression in glioma cells." (PMID 31186064, 2019). "Further, qRT-PCR showed that FAM224A was significantly upregulated in glioma tissues and cell lines when compared with NBTs and NHA." (PMID 31186064, 2019). "To understand the potential oncogenic mechanisms of FAM224A in glioma cells, we used a bioinformatics database (Starbase) to identify miR-590-3p as an target of FAM224A." (PMID 31186064, 2019). "CCK-8 assay, flow cytometry analysis, migration and invasion assays were conducted to determine the functions of FAM224A in glioma cells." (PMID 31186064, 2019). "In this study, we confirmed that A1CF and FAM224A were overexpressed in glioma tissues and cell lines." (PMID 31186064, 2019). "LncRNAs microarray analysis revealed that FAM224A was remarkably downregulated in glioma cells following knockdown of A1CF, implying that FAM224A may participate in A1CF-induced modulation on glioma cells." (PMID 31186064, 2019). "Furthermore, reduction of miR-590-3p obviously rescued the repression of malignant progression of glioma cells induced by FAM224A downregulation." (PMID 31186064, 2019). "In the present study, the endogenous expression of A1CF, FAM224A, miR-590-3p and ZNF143 were investigated in glioma tissues and cell lines." (PMID 31186064, 2019). "The Cell Counting Kit-8 assay, migration and invasion assays, and flow cytometry analysis were conducted to evaluate the function of A1CF, FAM224A, miR-590-3p, ZNF143 and ASAP3 in the malignant biological behaviors of glioma cells." (PMID 31186064, 2019). "Their roles in modulating malignant progression of glioma and the cross-talk between A1CF, FAM224A, miR-590-3p and ZNF143 were elucidated." (PMID 31186064, 2019). "Knockdown of A1CF or FAM224A obviously inhibited cell proliferation, migration and invasion, while promoted apoptosis in glioma cells when compared with the negative control groups." (PMID 31186064, 2019).
tumor (1 paper, 2019). "Collectively, knockdown of A1CF could increase miR-590-3p expression via downregulating FAM224A; however, the molecular mechanisms of miR-590-3p-induced tumor-suppressive functions still remain unknown." (PMID 31186064, 2019).